APC (APC regulator of Wnt signaling pathway)
Description:
Tumor suppressor. Promotes rapid degradation of CTNNB1 and participates in Wnt signaling as a negative regulator. APC activity is correlated with its phosphorylation state. Activates the GEF activity of SPATA13 and ARHGEF4. Plays a role in hepatocyte growth factor (HGF)- induced cell migration. Required for MMP9 up-regulation via the JNK signaling pathway in colorectal tumor cells. Associates with both microtubules and actin filaments, components of the cytoskeleton. Plays a role in mediating the organization of F-actin into ordered bundles. Functions downstream of Rho GTPases and DIAPH1 to selectively stabilize microtubules (By similarity). Acts as a mediator of ERBB2-dependent stabilization of microtubules at the cell cortex. It is required for the localization of MACF1 to the cell membrane and this localization of MACF1 is critical for its function in microtubule stabilization.
Synonyms: DP2.5; DP2; DP3; PPP1R46; BTPS2; DESMD; GS
Tractability: Small molecule: a structure with a bound ligand is known; a high-quality ligand is known. Antibody: UniProt places it where antibodies can reach, with high confidence; its Gene Ontology location is reachable by antibodies, with high confidence; the Human Protein Atlas places it where antibodies can reach. PROTAC: UniProt records ubiquitination sites on it; ubiquitination databases record sites on it; its protein half-life has been measured; a small molecule that binds it is known.
Target class: Other cytosolic protein
Gene: Protein-coding gene on chromosome 5 (112,707,498 to 112,846,239, forward strand). Ensembl gene ENSG00000134982.
Subcellular location: Cell junction, adherens junction; Cytoplasm, cytoskeleton; Cell projection, lamellipodium; Cell projection, ruffle membrane; Cytoplasm; Cell membrane
Subcellular location (Human Protein Atlas): Plasma membrane; Golgi apparatus
Pathways (Reactome):
Disease: APC truncation mutants are not K63 polyubiquitinated; APC truncation mutants have impaired AXIN binding; AXIN missense mutants destabilize the destruction complex; CTNNB1 S33 mutants aren't phosphorylated; CTNNB1 S37 mutants aren't phosphorylated; CTNNB1 S45 mutants aren't phosphorylated; CTNNB1 T41 mutants aren't phosphorylated; Signaling by GSK3beta mutants; Truncations of AMER1 destabilize the destruction complex
Signal Transduction: Beta-catenin phosphorylation cascade; Deactivation of the beta-catenin transactivating complex; Degradation of beta-catenin by the destruction complex; Disassembly of the destruction complex and recruitment of AXIN to the membrane
Metabolism of proteins: Ovarian tumor domain proteases
Programmed Cell Death: Apoptotic cleavage of cellular proteins
Gene Ontology:
Molecular function: beta-catenin binding; cadherin binding; dynein complex binding; gamma-catenin binding; microtubule binding; microtubule plus-end binding; protein binding; protein kinase binding; protein kinase regulator activity; ubiquitin protein ligase binding; protein-containing complex binding
Biological process: cell migration; DNA damage response; insulin receptor signaling pathway; mitotic cytokinesis; mitotic spindle assembly checkpoint signaling; negative regulation of canonical Wnt signaling pathway; negative regulation of cell cycle G1/S phase transition; negative regulation of cell population proliferation; negative regulation of cyclin-dependent protein serine/threonine kinase activity; negative regulation of G1/S transition of mitotic cell cycle; negative regulation of microtubule depolymerization; positive regulation of apoptotic process; positive regulation of cell migration; positive regulation of protein catabolic process; positive regulation of protein localization to centrosome; positive regulation of pseudopodium assembly; protein-containing complex assembly; regulation of attachment of spindle microtubules to kinetochore; regulation of microtubule-based movement; regulation of microtubule-based process; bicellular tight junction assembly; cell adhesion; cell fate specification; endocardial cushion morphogenesis; heart valve development; and 6 more
Cellular component: adherens junction; beta-catenin destruction complex; bicellular tight junction; catenin complex; centrosome; cytoplasm; kinetochore; lamellipodium; lateral plasma membrane; microtubule; nucleus; perinuclear region of cytoplasm; plasma membrane; ruffle membrane; cytoplasmic microtubule; cytosol; nucleoplasm; Wnt signalosome; cell junction; cytoskeleton; leading edge membrane; microtubule cytoskeleton; plasma membrane bounded cell projection
Genetic constraint (gnomAD): Loss-of-function variants: 58 observed, 225.07 expected, observed/expected ratio (o/e) 0.26, 90% interval 0.21 to 0.32. The upper end of that interval is the gene's LOEUF score, 0.32, which puts it in group 1 of 6, group 1 being the genes least tolerant of losing a copy. Missense variants: 3,276 observed, 3,403.5 expected, observed/expected ratio (o/e) 0.96, 90% interval 0.93 to 0.99. Synonymous variants: 1,216 observed, 1,195 expected, observed/expected ratio (o/e) 1.02, 90% interval 0.97 to 1.07.
Gene-disease validity (ClinGen):
ClinGen rates the evidence that APC causes each of these diseases.
classic or attenuated familial adenomatous polyposis (autosomal dominant): Definitive. An inherited diseases haracterized by the development of adenomas in the rectum and colon; classified into classic FAP and attenuated FAP.
gastric adenocarcinoma and proximal polyposis of the stomach (autosomal dominant): Definitive. An autosomal dominant disorder caused by specific pathogenic variants in the APC gene promoter, characterized by proximal gastric polyposis and an increased risk of gastric adenocarcinoma.
Cancer hallmarks: genome instability and mutations (suppresses); invasion and metastasis (promotes); suppression of growth (promotes); escaping programmed cell death (suppresses)
Homologues: Orthologues: chimpanzee APC (99% identical), macaque APC (98% identical), dog APC (94% identical), rabbit APC (94% identical), guinea pig APC (93% identical), mouse Apc (91% identical), rat Apc (90% identical), pig APC (90% identical), tropical clawed frog apc (76% identical), zebrafish apc (68% identical), Drosophila melanogaster Apc (20% identical), Drosophila melanogaster Apc2 (13% identical), and 1 more. Paralogues in human: APC2 (31% identical).
Diseases named in the same sentence as APC in open-access papers:
APC is named in the same sentence as 523 diseases in open-access papers, as found by Europe PMC text mining. Sharing a sentence is not in itself a finding about the gene and the disease. The quoted sentences say what the papers report.
colorectal cancer (1,062 papers, 1993 to 2026). A primary or metastatic malignant neoplasm that affects the colon or rectum. "Colorectal cancer is initiated by loss of APC, which drives expansion of LGR5+ intestinal stem cell (ISC) populations." (PMID 41856980, 2026). "Colorectal cancer (CRC) has traditionally been thought to develop through stepwise mutation of the APC tumour suppressor and other driver genes, coupled with expansion of positively selected clones." (PMID 41339549, 2026). "APC c.3920T>A; p.Ile1307Lys (I1307K), prevalent in individuals of Ashkenazi Jewish (AJ) origin, has been associated with a modestly increased colorectal cancer (CRC) risk." (PMID 40866199, 2025). "For example, in colorectal cancer, mutations in APC (a driver gene) are drivers only if they cause a truncation of the N-terminal part of the protein; otherwise (e.g., missense mutations), they are mostly considered passenger mutations." (PMID 40806438, 2025). "A promising application of JPI-547 is in cancers characterized by mutations in the tumor suppressor APC, which is frequently observed during early tumorigenesis, including in colorectal cancer." (PMID 40959288, 2025). "Consistently, AXIN2 knockout clones exhibited elevated β‐catenin protein levels, demonstrating that loss of AXIN2 impairs degradation of β‐catenin in APC mutant colorectal cancer cells." (PMID 39022865, 2025). "Mutations in the APC gene, present in over 80% of colorectal cancers, permanently disrupt this complex’s function, preventing cytoplasmic β-catenin from being phosphorylated and degraded." (PMID 41346579, 2025). "APC mutations are well established as driver mutations in colorectal cancer, and the APC protein is also involved in signalling pathways other than Wnt and is a cytoskeletal regulator." (PMID 40689426, 2025). "This TCR-like antibody approach provides a targeted therapeutic strategy for cancers with APC mutations and holds a potential promise of novel treatment for a subset of colorectal cancer patients." (PMID 40443649, 2025). "Our stem cell-derived colon organoid model revealed that a heterozygous APC mutation is sufficient to induce colorectal cancer formation." (PMID 40702333, 2025). "The majority of APC mutations observed in individuals with colorectal cancer produce APC proteins that are shortened at the C-terminus but have an intact N-terminal region." (PMID 40227591, 2025). "Colorectal cancer is one of the leading causes of cancer-related deaths worldwide, mainly due to aberrant Wnt/β-catenin signaling resulting from APC mutations." (PMID 40971369, 2025). "Familial adenomatous polyposis (FAP) is a hereditary disorder caused by constitutional pathogenic variants in the APC gene, leading to the development of up to hundreds of colorectal adenomas and a near-inevitable risk of colorectal cancer (CRC) if untreated." (PMID 40451978, 2025).
colorectal cancer (continued). "For instance, in colorectal cancer, mutations in the APC gene lead to uncontrolled Wnt signaling, causing excessive accumulation of β-catenin and subsequently activating oncogene expression." (PMID 40705722, 2025). "In this study, we focused on utilizing the C-terminal truncated adenomatous polyposis coli (APC) protein as a marker for genetic mutation, a trait present in 60–70% of colorectal cancer (CRC) patients." (PMID 39858085, 2025). "Though patients with APC germline variants are typically at risk for colorectal cancers, extracolonic malignancies like medullary thyroid cancer and medulloblastomas are included in the syndrome." (PMID 41465149, 2025). "Our findings revealed that mRNA expression of both P2X7A and P2X7B isoforms, as well as A2A, was significantly elevated in APC-mutated colorectal cancer patient samples compared to wild-type controls." (PMID 40759630, 2025). "In a number of colorectal cancers, a mutation in the APC gene appears to be a key carcinogenic factor." (PMID 40165370, 2025). "Consistent with the theory that most colorectal cancers begin with biallelic loss-of-function variants of APC, APC variants were detected in 24 of 32 (75%) tumor DNAs." (PMID 40004106, 2025). "In colorectal cancer samples, common APC mutations and Wnt ligand overexpression contribute to β-catenin nuclear localization and EMT." (PMID 40943055, 2025). "Our data show that AXIN2‐mediated feedback inhibition of the Wnt pathway is active in APC mutated colorectal cancer cells." (PMID 39022865, 2025). "Consistent with the theory that APC is a gatekeeper in colorectal cancer, APC somatic DNA variants were detected in 24 of 32 samples (75%), for a total of 41 variants, and LOH was observed in 15 of these samples." (PMID 40004106, 2025). "In microsatellite-stable colorectal cancer driven by APC mutations, the APC mutation causes sustained nuclear translocation of β-catenin, activating stemness genes." (PMID 41346579, 2025). "APC is a tumour suppressor gene located in the long arm of chromosome 5 that is highly implicated in the pathogenesis of colorectal cancers." (PMID 40177144, 2025). "More than 70% of adenoma formation is accompanied by APC gene mutations, indicating that APC gene mutations are closely associated with precancerous lesions in colorectal cancer." (PMID 41410283, 2025). "Among individuals with mutations in CHEK2, BRCA2, PMS2, and APC, a high proportion reported a family history of breast, ovarian, prostate, pancreatic, or colorectal cancer (8 out of 11 considered patients)." (PMID 41294693, 2025). "To investigate the activity of the AXIN2 feedback in APC‐mutated colorectal cancer in a clean system, we generated SW480 AXIN2 knockout cells using the CRISPR/Cas9 technique." (PMID 39022865, 2025). "Somatic APC mutations in colorectal cancers are typically nonsense variants and insertion and/or deletion mutations that result in amino acid truncation." (PMID 41488735, 2025). "In approximately 80% of patients with sporadic colorectal cancer, the APC gene is mutated; moreover, approximately 50% of patients having colon cancer with wild-type APC harbor mutations in the β-catenin gene." (PMID 40649987, 2025). "Colorectal cancer (CRC) subpopulations with mutations in the tumor suppressor gene APC are more likely to be inactivated by overexpression of β-catenin." (PMID 40240755, 2025). "Colorectal cancer (CRC) carcinogenesis in carriers of pathogenic APC (path_APC) and pathogenic mismatch repair gene (path_MMR) variants is initiated by a second hit affecting the corresponding wild-type allele." (PMID 39849512, 2025).
colorectal cancer (continued). "For example, a 3-mm TA harbored one of the highest MB of 6.45, with pathogenic mutational defects in numerous colorectal cancer driver genes (e.g., APC, SOX9, TCF7L2, ASXL1, ERBB3, MAP2K1, and PTPRS)." (PMID 40757636, 2025). "APC mutations are also found in 80% of colorectal adenomas and metastatic colorectal cancers and are among the earliest mutations in colorectal cancer development." (PMID 40818609, 2025). "It is believed that TDO2 plays a crucial role as a downstream effector in APC-deficient colorectal cancer." (PMID 40136551, 2025). "Patients with Familial Adenomatous Polyposis Coli (FAP) carry a germline mutation in the APC gene, which is mutated in ∼77 % of colorectal cancers." (PMID 39755235, 2025). "For instance, they will unlock greater value in fields including colorectal cancer research, where they have revealed how mutations in the APC regulator of the Wnt signaling pathway (APC) gene drive tumorigenesis through the Wnt signaling pathway." (PMID 41359105, 2025). "APC is a tumor suppressor gene with a very high mutation rate in colorectal cancer, and its mutation and inactivation are key early events in colorectal cancer tumor formation." (PMID 40642070, 2025). "A recent study evaluated 60 patients with APC mutations and 25 wild type individuals with colorectal cancer who received immune checkpoint therapy." (PMID 39944699, 2025). "We show that colorectal cancer (CRC) with loss-of-function mutation in the APC tumor suppressor depends on an oncogenic translation program regulated by the ability to sense phosphorylated eIF2α (p-eIF2α)." (PMID 40016419, 2025). "In colorectal cancer cells, mutations in the APC gene activate the Wnt/β‐catenin pathway, resulting in increased c‐MYC transcription." (PMID 40525649, 2025). "APC mutations play a central role in colorectal tumorigenesis, as evidenced by their high prevalence in colorectal cancer." (PMID 41285904, 2025). "In cancer cells, these alterations result in genomic instability and the accumulation of oncogenic mutations, such as those in the APC gene in colorectal cancer, which drive tumor aggressiveness and therapy resistance." (PMID 40563999, 2025). "The association between TLS and mutations in the PI3K‐mTOR pathway in renal clear cell carcinoma, BRAF mutations in colorectal carcinoma, and APC germline mutations in hepatoblastoma has been reported in studies." (PMID 40396416, 2025). "Mutations in APC, β-catenin, or other components of this pathway mediate the transition of single preneoplastic cells to aberrant crypt foci and then to adenoma and colorectal carcinoma." (PMID 40624028, 2025). "More than 90% of colorectal cancers have activating somatic mutations in the WNT pathway (APC loss or β-catenin mutation), thus the WNT pathway activation is considered as a prerequisite for colorectal cancer pathogenesis." (PMID 38051091, 2024). "This stands in stark contrast to other mutations such as JAK2V617F or IDH2R140Q in leukemia, or APC in colorectal cancer, where previous studies have suggested a continued requirement for disease maintenance." (PMID 39553934, 2024). "APC mutations have also been identified in colorectal cancer and epithelial lesions in the DMH/AOM rat model, although to a lesser extent and in a different region than that observed in humans." (PMID 39339648, 2024). "Familial adenomatous polyposis (FAP) is an autosomal dominant syndrome caused by germline variants in the APC gene, leading to the development of numerous colorectal polyps and significantly increases the risk of colorectal cancer." (PMID 39632802, 2024). "Colorectal cancer is often associated with loss of heterozygosity of WNT regulator APC, causing hyperplasia of the epithelium." (PMID 39060237, 2024). "We provide evidence that in human colorectal cancer cells with a hyperactive WNT pathway due to APC mutations, knockout of RNF43 promotes cancer cell growth by activating EGFR signaling." (PMID 38260423, 2024).